SREBF1 (sterol regulatory element binding transcription factor 1)
Diseases named in the same sentence as SREBF1 in open-access papers (continued):
Sharing a sentence is not in itself a finding about the gene and the disease.
colorectal cancer (35 papers, 2017 to 2026). A primary or metastatic malignant neoplasm that affects the colon or rectum. "Survival analysis demonstrated that SREBF1 overexpression serves as an independent risk factor for poor prognosis in colorectal cancer patients." (PMID 40668814, 2025). "In summary, our comprehensive analysis of SREBF1 in colorectal cancer reveals that its expression is significantly associated with clinical outcomes, lipid metabolism, and immune cell infiltration." (PMID 40668814, 2025). "RT-PCR analysis of clinical specimens also demonstrated that the expression level of SREBF1 was significantly higher in colorectal cancer tissues compared to paired adjacent normal tissues." (PMID 40668814, 2025). "Despite the comprehensive analysis of SREBF1 in colorectal cancer, there are inevitable limitations in this study." (PMID 40668814, 2025). "This study highlights the regulatory role of SREBF1 in pan-cancer contexts and provides novel insights into its potential as a prognostic biomarker and therapeutic target, particularly in colorectal cancer." (PMID 40668814, 2025). "Pan-cancer analysis revealed significant upregulation of SREBF1 in multiple cancer types, including colorectal cancer (CRC)." (PMID 40668814, 2025). "To further validate the function of SREBF1 in tumor proliferation and migration, we selected the colorectal cancer cell line HCT116 to study the effect of SREBF1 knockdown in vivo." (PMID 40668814, 2025). "Our research found that the significant overexpression of SREBF1 and its association with poor prognosis in CRC, we further confirmed through cell experiments that SREBF1 promotes the proliferation and migration of colorectal cancer cells." (PMID 40668814, 2025). "Second, further clinical trials are required to clarify the therapeutic potential of targeting SREBF1 in colorectal cancer." (PMID 40668814, 2025). "In this study, we discovered that high expression of SREBF1 was positively correlated with poor prognosis in colorectal cancer, and significantly inhibited the proliferation and migration of colorectal cancer cells after SREBF1 was knocked down." (PMID 40668814, 2025). "Compared to the normal colorectal cell line NCM460, we identified a significantly increase in both mRNA and protein levels of SREBF1 in human colorectal cancer cell lines, particularly in the HCT116 and LS174T cell lines." (PMID 40668814, 2025). "This creates therapeutic rationale for combining SREBF1 inhibitors (fatostatin) with anti-PD-1/PD-L1 agents in colorectal cancers." (PMID 40668814, 2025). "Moreover, ilexgenin A inhibits HIF-1α expression, consequently downregulating sterol regulatory element-binding transcription factor 1 (SREBF1) expression and lipid accumulation in colorectal cancer cells." (PMID 34575983, 2021).
pancreatic cancer (34 papers, 2014 to 2025). "Further studies have shown that BHLHE40 regulates the transcription of element-binding factor 1 (SREBF1), and that the bHLHE40-SREBF1 axis regulates the protection of pancreatic cancer cells from ferroptosis." (PMID 40959280, 2025). "We also demonstrate the in vivo effect of Yarrow SFE, which brakes tumor growth in a xenograft mouse model of pancreatic cancer, together with SREBF1 downregulation in the injected tumors." (PMID 30913248, 2019). "In pancreatic cancer, increased expression of SREBF1 was predictive of poor prognosis and depletion of SREBF1 resulted in suppression of tumor growth." (PMID 26575021, 2015). "Activation of LXR leads to strong up-regulation of SREBF1 (sterol regulatory element-binding protein 1c) in breast, colon, pancreatic cancer cells, and is a regulator of lipogenesis and glucose metabolism." (PMID 25184494, 2014). "Triptonide exerts anti-cancer effects through down-regulation of various oncogenic genes, including β-catenin, cMyc, Notch1, LXRα, SREBF1, particularly, triptonide directly binds to its receptor LXRα, reduces LXRα protein stability in pancreatic cancer cells, and exerts potent anti-cancer effect." (PMID 34922602, 2021). "SREBF1 (Sterol Regulatory Element Binding Transcription Factor), ASS1 (Argininosuccinate Synthase) and HSPA-5 (Homo Sapiens Heat Shock protein 5) were selected for further validation by RT-qPCR due to their known association with tumor processes and with pancreatic cancer development." (PMID 30913248, 2019). "We also compared the expression of LXRβ and known target genes SREBF1, ABCA1, ABCG1, FASN, and SCD in pancreatic cancer tissue to normal pancreas tissue and found that transcript levels of LXRβ and its target genes are elevated in the tumor tissues." (PMID 33348693, 2020). "In a previous work, we have demonstrated that Yarrow (Achillea millefolium) supercritical fluid extract (Yarrow SFE) downregulates the expression of the lipogenic genes SREBF1, FASN, and SCD1 in a pancreatic cancer model." (PMID 31888081, 2019). "The sterol response element binding factor-1 (SREBF1) was known to be involved in the DNA repair mechanisms in cancer cells, the activated LXRs are reported to inhibit the activity of SREBF1 via LXR-SREBF1-PNKP axis and significantly promote apoptotic mediated cell death of pancreatic cancer cells." (PMID 38550382, 2024).
colon carcinoma (31 papers, 2015 to 2025). "The following results demonstrated that the expression levels of the total SREBF1 protein were elevated in primary tissues of Colon Cancer (COAD), and LUAD compared with normal tissues." (PMID 40668814, 2025). "The effect of Yarrow SFE on SREBF1 downregulation seems to be highly specific, as similar results were obtained in other cancer types, such as in SW-620, a colon cancer cell line." (PMID 30913248, 2019). "Finally, estimation of SREBF1 mRNA levels may also not reflect the activity of the protein it encodes, in particular its mature cleaved form, which has been shown to play a key role in the control of metabolism in colon cancer cells." (PMID 34206240, 2021).
melanoma (31 papers, 2014 to 2025). A malignant, usually aggressive tumor composed of atypical, neoplastic melanocytes. "Our analysis suggested that SREBF1 was predominantly strongly or positively expressed in tumor tissue originating from breast, and melanoma." (PMID 40668814, 2025). "We depleted SREBF1 with ASO-4 in several melanoma cell lines cultured under the three medium conditions, to obtain dose-response curves and IC50 values." (PMID 31316083, 2019). "We demonstrated in melanomas that inhibition of SREBF1 by 5 nM ASO-4 treatment results in 50% reduction in the expression of multiple DNFA genes." (PMID 31316083, 2019). "The enhanced ACAT2 expression observed in lipid-starved resistant melanoma cells could be ascribed to mechanisms involving SREBF1/2 expression, which control upstream lipid metabolism pathways, and display upregulation in resistant cells." (PMID 35912092, 2022). "To further confirm the in vivo anti-melanoma activity of T0901317 was mediated through LXR signaling, we analyzed the expression of LXR target genes, ABCA1 and SREBF1, in tumors, and found that expressions of ABCA1 and SREBF1 were increased in T0901317-treated melanoma." (PMID 24564864, 2014). "In addition, Treg cells repress IFN-γ derived from CD8 + T-cells to sustain TAMs by promoting sterol regulatory element binding transcription factor 1 (SREBP1)-dependent lipid metabolism, while inhibition of the SREBP1 pathway cooperates with anti-PD-1 therapy to reduce melanoma tumor growth." (PMID 40108693, 2025). "To evaluate potential activators of DNFA expression, we depleted SREBF1, SREBF2, and co-activators MED15 and CREBBP28 with siRNAs, and examined DNFA expression across three melanoma cell lines: HT-144, A375 and MEL-JUSO." (PMID 31316083, 2019). "The systems biology analysis performed in this study revealed that upregulation of self-renewing genes in CD271+ melanoma cells occurs in response to the activation of E2F, MYC, and SREBF1 promoter-containing elements." (PMID 31118427, 2019). "Upon T0901317 treatment, expressions of LXR target genes, ABCA1 and SREBF1, were induced in B16F10, indicating LXRs were functional in B16F10 melanoma cell line." (PMID 24564864, 2014). "To test whether SREBP1 drives elevated DNFA enzyme expression in melanomas, we depleted the SREBP1 mRNA (SREBF1) with antisense oligonucleotides (ASOs) and siRNAs in HT-144 cells." (PMID 31316083, 2019).
ovarian carcinoma (23 papers, 2012 to 2026). A malignant neoplasm originating from the surface ovarian epithelium. "CircATP2B4 regulates SREBF1 in ovarian cancer by binding to miR-532-3p, which not only reduces oxidative stress by increasing fatty acid synthesis but also promotes TAM polarization into M2." (PMID 38523627, 2024). "For instance, in ovarian cancer, exosome-derived circATP2B4 can be delivered to infiltrating macrophages and induce M2-type polarization through modulation of the miR-532-3p/SREBF1/PI3Kα/AKT axis, leading to immunosuppression and ovarian cancer metastasis." (PMID 37819576, 2023). "Microarray data analysis confirmed that HMGCR is strongly repressed in ovarian carcinomas, while induction of SREBF1 is in accordance with our experimental data showing increased SREBF1c in ovarian clinical cancer specimens." (PMID 26807200, 2015). "We found that suppression of SREBF2 in ovarian cancers results in down-regulation of cholesterogenic target genes such as the DHCR7, while induction of SREBF1 is associated with increased expression of lipid synthesis genes such as the SCD1, which was found highly elevated." (PMID 26807200, 2015). "It clusters together genes with common expression profiles and confirms that the expression of SREBF1, SCD1 and FASN is coordinately up-regulated in ovarian cancers." (PMID 26807200, 2015).
lung carcinoma (22 papers, 2016 to 2025). "Six different lung cancer cell lines (H1299, H1563, H1975, H1573, H1437, and H661) were cultured in BM for 18 h or 48 h and analyzed for LD formation and SREBF1 expression." (PMID 36139614, 2022). "In this study, we explored the relationship between lipid droplet (LD) formation, SREBF1 expression, and lung cancer cell sensitivity to chemotherapeutics, such as cisplatin and etoposide." (PMID 36139614, 2022). "A direct relationship between SREBF1 expression and LD formation can be found in lung cancer cell lines cultured in serum-free BM." (PMID 36139614, 2022). "The methylation levels of three CpGs (located at LMNA, SREBF1, and ABCG1) in whole blood were inversely associated with lung cancer risk." (PMID 33939316, 2021). "The SREBF1 value as a biomarker might be lost during later stages of lung cancer, which are characterized by a persistent and advanced inflammatory state." (PMID 36139614, 2022). "The SREBF1 gene was one of the highlighted genes linking oncogenic signaling with lipid metabolism, and an elevated SREBF1 expression was correlated with cancer progression and metastasis of several cancer types, including lung cancer." (PMID 36139614, 2022). "Indeed, our initial experiments with different lung cancer cell lines confirmed that higher expression levels of SREBF1 were related to a more pronounced LD formation." (PMID 36139614, 2022). "The cg11024682 and cg06500161 annotated to SREBF1 and ABCG1 genes, could mediate the associations of BMI and lung cancer risk." (PMID 33939316, 2021). "In this study, we found that cg11024682 (in SREBF1) and cg06500161 (in ABCG1) could mediate 45.3% and 19.5% of the association between BMI and decreased lung cancer risk, respectively." (PMID 33939316, 2021). "More importantly, cg11024682 in SREBF1 and cg06500161 in the ABCG1 gene could mediate 45.3% and 19.5% of the BMI‐NSCLC association, respectively, suggesting the biological role of DNA methylation on the association between BMI and reduced lung cancer risk in the Chinese populations." (PMID 33939316, 2021). "We also found that miR-195 could directly bind to the mRNAs of SREBF1, FASN and ACACA in lung cancer cells resulting in decreases in lipid droplet formation induced by PM2.5 exposure." (PMID 36496421, 2022). "Therefore, we checked for SREBF1 expression in tumor and adjacent nontumor tissues from lung cancer patients." (PMID 36139614, 2022).
gastric cancer (20 papers, 2018 to 2026). A primary or metastatic malignant neoplasm involving the stomach. "Researchers identified alkannin as a clinically promising natural product against gastric cancer (GC), and elucidated a previously unreported ferroptosis mechanism on lipid homeostasis regulation via the c-Fos/sterol regulatory element binding transcription factor 1 (SREBF1) axis." (PMID 41502519, 2025).
liver fibrosis (20 papers, 2013 to 2026). "We focused on SOCS3, SREBF1, and TXNIP, genes known to be implicated in inflammatory pathways and liver fibrosis." (PMID 39941038, 2025). "For example, elevated circulating miR-185 was reported in HBV-related liver fibrosis, which could target SREBF1 and increase expression of Col 1A1 and α-SMA33." (PMID 32467578, 2020). "Therefore, inhibition of SREBF1 expression following overexpression of miR-185 might be a mechanism associated with the increases in COL1A1 and a-SMA levels during liver fibrosis." (PMID 27677421, 2016). "miR-185 targeted SREBF1, and increased expression of COL1A1 and a-SMA genes that are hallmarks of liver fibrosis." (PMID 27677421, 2016). "Furthermore, miR-185 targets SREBF1, and increases expression of COL1A1 and a-SMA genes that are involved in liver fibrosis." (PMID 27677421, 2016). "Furthermore, miR-185 targeted SREBF1 and increased expression of COL1A1 and a-SMA genes, which are hallmarks of liver fibrosis." (PMID 27677421, 2016).
acne (15 papers, 2013 to 2025). An inflammatory process of the sebaceous glands which is characterized by comedones, nodules, papules and/or pustules on the skin. "In fact, IGF-1 has been shown to induce SREBF1 expression and lipogenesis in SEB-1 sebocytes via the activation of the PI3K/AKT pathway, whereas a low glycemic diet, which decreases IGF-1 serum levels, reduces SREBF1 expression in the sebaceous glands (SGs) of acne patients." (PMID 37998335, 2023).
breast tumor (14 papers, 2015 to 2025). "It is also noteworthy that from the bar chart view, selecting UGCG or SREBF1 as potential biomarkers would be unlikely as most normal breast tumour samples also expressed high levels of these genes." (PMID 32577155, 2020).
glioma (14 papers, 2017 to 2025). A benign or malignant brain and spinal cord tumor that arises from glial cells (astrocytes, oligodendrocytes, ependymal cells). "Over expression of SREBF1 has also been implicated in other cancers (e.g., ovarian, pancreatic and glioma) and has been found to facilitate invasion." (PMID 35710732, 2022). "Upregulated genes, such as EGFR and MYO1C, are associated with glioma cell proliferation and migration, whereas downregulated genes such as MMP11 and SREBF1 are related to cell adhesion and lipid metabolism (bottom)." (PMID 29587824, 2018). "Genes involved in the regulation of the mevalonate pathway (INSIG1 and SREBF2 but not SREBF1) were also downregulated in dense NHAs but not glioma cells." (PMID 28118603, 2017).
Hypercholesterolemia (12 papers, 2017 to 2025). An increased concentration of cholesterol in the blood. "A rare variant of the SREBF1 gene (rs115855236, chr17:17820281) was identified in proband P83 and a son of this proband (patient P84) with clinical signs of familial hypercholesterolemia." (PMID 34834584, 2021). "In our study, hypermethylation of promoters of key genes regulating cholesterol metabolism such as PCSK9, LRP1, ABCG1, ANGPTL4, SREBF1 and NR1H2, were found in obese patients with hypercholesterolemia." (PMID 33028190, 2020).
lipodystrophy (12 papers, 2008 to 2025). A congenital or acquired disorder characterized by abnormal loss or redistribution of the adipose tissue in the body. "This reduced binding resulted in SREBF-1 dysregulation, and abnormal expression of downstream SREBF-1 target genes contributing to lipodystrophy in patients." (PMID 33142761, 2020).
coronary artery disease (11 papers, 2017 to 2026). "Using genetic sequence variants to model exposure to differential DNA methylation and tissue-specific gene expression, we found differential methylation and expression of SREBF1 to be implicated in BMI, adiposity-related traits, and coronary artery disease." (PMID 28095459, 2017). "Genetic instrumental variable analysis of altered methylation at one of the 83 replicated CpG loci, cg11024682 (intronic to sterol regulatory element binding transcription factor 1, SREBF1), was associated with BMI, adiposity-related traits, and coronary artery disease." (PMID 36397166, 2022). "We provide support for a role of genomic regulation of a lipid metabolism transcription factor, SREBF1, in adiposity and coronary artery disease." (PMID 28095459, 2017). "Similarly, QTLs for genes linked to coronary artery disease risk (e.g. LPL, SREBF1, GIT1, SKIV2L, MAP3K11/MLK3) were associated with colocalization sites linking coronary artery disease with mean platelet volume, lymphocyte, and/or reticulocyte counts." (PMID 32600345, 2020). "Regulation of SREBF1 is an underexplored target for the prevention of coronary artery disease." (PMID 28095459, 2017). "Genetic instrumental variable analysis of alterations in methylation at one of the 83 replicated CpGs, cg11024682 (intronic to sterol regulatory element binding transcription factor 1 [SREBF1]), demonstrated links to BMI, adiposity-related traits, and coronary artery disease." (PMID 28095459, 2017).
non-small cell lung carcinoma (11 papers, 2021 to 2026). A group of at least three distinct histological types of lung cancer, including non-small cell squamous cell carcinoma, adenocarcinoma, and large cell carcinoma. "Research has indicated that methylation at cg11024682 in SREBF1 may mediate the association between BMI and non-small cell lung cancer risk." (PMID 40702573, 2025). "Nevertheless, under basal conditions, SREBF1 expression in cancer cells correlated with LD levels, and the lower expression of SREBF1 in tumors than in adjacent nontumor tissues showed a prognostic value for overall better survival of patients with non-small-cell lung cancer." (PMID 36139614, 2022).